ALOX15 (arachidonate 15-lipoxygenase)
Diseases named in the same sentence as ALOX15 in open-access papers (continued):
Sharing a sentence is not in itself a finding about the gene and the disease.
Hodgkins lymphoma (2 papers, 2014 to 2019). A heterogeneous group of malignant lymphoid neoplasms of B-cell origin characterized histologically by the presence of Hodgkin and Reed-Sternberg (HRS) cells in the vast majority of cases. "The critical role of UTX in ALOX15 expression was confirmed in human monocytes and the Hodgkin lymphoma (HL) cell line L1236, but was in these cells not related to H3K27me3-demethylase activity." (PMID 24465480, 2014).
hyperlipidemia (2 papers, 2024 to 2025). "Alox15 signaling is involved in liver injury pathogenesis in experimental models of hyperlipidemia-derived MAFLD and enhances neutrophil recruitment and inflammatory response." (PMID 38791066, 2024).
infertile (2 papers, 2020 to 2024). "This study establishes a potential link between ALOX15 and male factor infertility, demonstrated by the propensity of this enzyme to cause lipid peroxidation and an overproduction of 4HNE that features in the spermatozoa of infertile patients." (PMID 33396527, 2020). "In infertile patients, the strong signal of ALOX15 in the midpiece of the sperm tail seems to indicate mitochondrial involvement." (PMID 39273059, 2024). "Through the assessment of patient samples, our study has revealed a significant increase in the abundance of the ALOX15 enzyme in the spermatozoa of a subset of infertile males with idiopathic infertility." (PMID 33396527, 2020). "Comparison of the sperm lysates from three representative normozoospermic individuals and three representative individuals with unexplained infertility revealed a highly significant increase in ALOX15 abundance in the infertile samples (p < 0.0081)." (PMID 33396527, 2020). "Upon examination of ALOX15 in the spermatozoa of infertile patients compared to their normozoospermic counterparts, we observed significantly elevated levels of ALOX15 protein abundance in the infertile population and an increase in 4-hydroxynonenal adducts." (PMID 33396527, 2020). "Finally, the immunolocalization of ALOX15, a lipoxygenase enzyme that promotes lipid degradation, confirmed the possible presence of ferroptosis in ejaculated sperm of infertile patients with varicocele and urogenital infections." (PMID 39273059, 2024). "Given that our data indicate that ALOX15 is the primary lipoxygenase family member involved in the catalysis of peroxidised lipids released from the human sperm membrane, we elected to examine the abundance of ALOX15 in the spermatozoa of fertile and infertile men." (PMID 33396527, 2020). "In view of these promising data, this study was designed to generate additional mechanistic insights into the regulation of lipoxygenase driven lipid peroxidation cascades in human spermatozoa and examine the relative abundance of ALOX15 in the spermatozoa of infertile men." (PMID 33396527, 2020). "Notably, elevated levels of ALOX15 detected in infertile sperm lysates were accompanied by a commensurate increase in lipid peroxidation levels in the sperm of these individuals, as measured by the abundance of 4HNE protein adducts, a common deleterious outcome downstream of lipid peroxidation." (PMID 33396527, 2020).
nasopharyngeal carcinoma (2 papers, 2020). A carcinoma arising from the nasopharyngeal epithelium. "Because of the downregulation of the ALOX15 gene, the suppressor or inhibitor of inflammation decreases, causing the pro-inflammatory agent to activate in the chronic inflammatory process that triggers nasopharyngeal cancer." (PMID 32986378, 2020). "The hypothesis that the ALOX15 gene expression is down-regulated in the development of nasopharyngeal cancer can be presumed to be the same regulation." (PMID 32986357, 2020).
nonalcoholic fatty liver disease (2 papers, 2017 to 2023). "Alox15, the gene encoding for 12/15-lipoxygenase (12/15-LOX), is markedly up-regulated in livers from apolipoprotein E-deficient (ApoE2/2) mice, which spontaneously develop nonalcoholic fatty liver disease." (PMID 36830070, 2023).
periventricular leukomalacia (2 papers, 2022 to 2023). Periventricular leukomalacia (PVL) is a brain injury disorder characterized by the death of the white matter of the brain due to softening of the brain tissue. "Moreover, Alox15 expression is increased in the brains of periventricular leukomalacia (PVL) patients." (PMID 36932456, 2023).
pituitary adenoma (2 papers, 2019 to 2024). "The pro-carcinogenic role of ALOX15 isoforms was highlighted following an increase in expression and activity in pituitary adenomas with larger tumor size and a higher degree of invasion." (PMID 38612771, 2024). "In the pathogenesis of pituitary adenomas, the expression of both ALOX15 and ALOX15B as well as their metabolites 15-(S)-HETE, 13-(S)-HODE are significantly elevated respectively." (PMID 38612771, 2024). "This pro-carcinogenic role of ALOX15 isoforms was highlighted following an increase in expression and activity in pituitary adenomas with larger tumor size and higher degree of invasion." (PMID 38612771, 2024). "In the pathogenesis of pituitary adenomas, the expression of both ALOX15 and ALOX15B as well as their metabolites 15-(S)-HETE, 13-(S)-HODE are significantly elevated." (PMID 38612771, 2024).
rectal cancer (2 papers, 2016 to 2022). A primary or metastatic malignant neoplasm that affects the rectum. "ALOX12 (rs2073438) was associated with a lower risk of rectal cancer.ALOX15 (rs4796535 and rs2619112) was associated with an increased risk of rectal cancer." (PMID 35928873, 2022). "In regards to colon and rectal cancers, certain individuals may benefit largely from including LCn-3 PUFA in their diets while others do not, as demonstrated by polymorphisms in ALOX12, ALOX15 and PGES genes." (PMID 26891335, 2016).
renal fibrosis (2 papers, 2021 to 2023). A final common manifestation of a wide variety of chronic kidney diseases characterized by glomerulosclerosis and tubulointerstitial fibrosis. "In the present study, using the 5/6 Nx mouse model, we found that ALOX15 deletion ameliorated kidney dysfunction and renal fibrosis in a CKD model." (PMID 33595729, 2021). "Furthermore, we found that, at least in part by mechanism, TG2 markedly exacerbates renal fibrosis though the enhanced expression of ALOX15 and a metabolite derived from ALOX15 activity." (PMID 36864028, 2023). "Furthermore, we found that ALOX15 was an important factor acting in the downstream of intracellular TG2 activity in the polarization of M2 macrophages and exacerbated renal fibrosis." (PMID 36864028, 2023). "Since ALOX15 expression in macrophage is detected in vivo, a possible problem is that in vitro experiments using BMDMs do not adequately reflect the in vivo situation of renal fibrosis." (PMID 36864028, 2023). "Therefore, we investigated whether and how ALOX15 plays a role in CKD in terms of kidney dysfunction and renal fibrosis." (PMID 33595729, 2021). "The resident (peritoneal) macrophages have been reported to have a larger population of ALOX15-positive cells compared to BMDMs, suggesting that TG2 in BMDMs may involves in not only its own M2 polarization but also that of resident macrophages during renal fibrosis." (PMID 36864028, 2023).
steatosis (2 papers, 2023). Increased lipid within the cytoplasm of cells. "ALOX15 knockdown in senescent HepG2 cells attenuated hepatocyte steatosis induced by the senescent hepatocyte-conditioned medium." (PMID 38071367, 2023). "In a paracrine manner, the increased expression of ALOX15 in senescent hepatocytes and macrophages induced 9-HODE and 13-HODE production and promoted steatosis." (PMID 38071367, 2023).
acute lymphoblastic leukemia (1 paper, 2023). Leukemia with an acute onset, characterized by the presence of lymphoblasts in the bone marrow and the peripheral blood. "In addition, ALOX15 has been reported to be involved in the occurrence of cell ferroptosis in RSL3-induced acute lymphoblastic leukemia (ALL)." (PMID 37849828, 2023).
acute myeloid leukemia (1 paper, 2024). Acute myeloid leukemia (AML) is a group of neoplasms arising from precursor cells committed to the myeloid cell-line differentiation. "It inhibits ferroptosis in TSCC cells by inhibiting miR-125b-5p and enhancing SLC7A11, while in acute myeloid leukemia (AML), muscle ARNT-Like protein-1 (Bmal1) prevented RSL3-induced ferroptosis through EZH2-mediated EBF3 methylation to inhibit the expression of EBF3 and ALOX15." (PMID 39518098, 2024).
adenomyosis (1 paper, 2025). The growth of endometrial tissue inside the muscular wall of the uterine corpus. "Genes that promote ferroptosis, such as ACSL1, ALOX15, STEAP3, and SLC11A2, were upregulated in adenomyosis." (PMID 40911580, 2025).
airway hyperresponsiveness (1 paper, 2023). "Mice deficient in 12/15-LOX (Alox15−/−) demonstrated better lung function, as measured by airway hyperresponsiveness (AHR), during fungal asthma." (PMID 37253655, 2023). "Results here demonstrate that mice deficient in 12/15-LOX (Alox15−/−) had significantly lower total lung dynamic resistance and airway hyperresponsiveness (AHR) during A. fumigatus-associated allergic fungal asthma." (PMID 37253655, 2023).
alcoholic hepatitis (1 paper, 2020). Acute hepatitis resulting from ingestion of alcohol. "Since inflammation is a main driver of disease progression in alcoholic hepatitis, we investigated the impact of endogenous ALOX15-dependent lipid mediators and exogenously applied LXA4 on AH development." (PMID 32760397, 2020).
Autoimmunity (1 paper, 2024). The occurrence of an immune reaction against the organism's own cells or tissues. "Agreeing with the proposed role of these lipids in driving arterial coagulation in vivo, Alox15−/− mice, which lack many eoxPL, generated smaller thrombi in an arterial model of AAAs, and higher levels of eoxPL are associated with prothrombotic autoimmunity." (PMID 39674322, 2024).
bladder cancer (1 paper, 2025).
bone tumor (1 paper, 2018). "The present study was carried out to elucidate the effect of histone acetylation on Alox15 expression in SH-SY5Y cells, which were originally derived from a bone tumor." (PMID 29235036, 2018).
cholestasis (1 paper, 2023). Impairment of the bile flow caused by obstruction within the liver, or outside the liver in the bile duct system. "The genes regulated in all pathways, Cyp1a1, Cyp1a2, Cyp2a1, Cyp2b1, Cyp4a8, Cyp2c11, Rdh16, Alox15, Ephx2, Sult2a1, and Acox2, were the potential targets for ZYP treatment of cholestasis." (PMID 37881184, 2023).
colorectal polyp (1 paper, 2019). "Furthermore, we detected the expressions of ALOX5, ALOX12, ALOX15 and ALOX15B in colorectal polyp." (PMID 31528237, 2019).
dental caries (1 paper, 2023). The decay of a tooth, in which it becomes softened, discolored, and/or porous. "In this case–control study, 15 SNPs in ALOX15, AMBN, AMELX, KLK4, TFIP11, and TUFT1 genes were analyzed in 150 children with primary dentition and 611 children with permanent teeth with/without dental caries from the European Longitudinal Study of Pregnancy and Childhood (ELSPAC) cohort." (PMID 36422720, 2023).
depression (1 paper, 2021). "For instance, the oncogene S100A9 was upregulated while the tumor suppressor genes HDC, AKAP12, SFRP5, and ALOX15 were downregulated in depression groups." (PMID 34650925, 2021).
E. coli infection (1 paper, 2018). "Importantly, based on our results, E. coli infection causes down-regulation of genes encoding lipid biosynthesis enzymes including ALOX15, FASN, GPAM, TM7SF2 that are involved in milk production." (PMID 29470489, 2018).
eosinophilic esophagitis (1 paper, 2025). Eosinophilic esophagitis (EoE) is a chronic, allergic disease of the esophagus characterized clinically by symptoms of esophageal dysfunction (including vomiting, dysphagia, feeding disorders, food impaction and abdominal pain) which persist after treatment with proton pump inhibitors (PPIs). "15(S)-hydroxyeicosatetraenoic acid (15(S)-HETE) is a metabolite derived from the molecular pathway of ALOX-15, an enzyme involved in the pathogenesis of Th2-mediated diseases such as eosinophilic esophagitis (EoE)." (PMID 41375879, 2025).
Hyperglycemia (1 paper, 2019). An increased concentration of glucose in the blood. "Based on previous studies, we found the dysregulations of Plin2, Alox15, Nr1i2, and Nr1d1 genes related to lipid metabolism might implicate to the disorders of the hypothalamus in the diabetic GK rats and contribute to the hyperglycemia in them." (PMID 31579613, 2019).
hypersplenism (1 paper, 2024). Overactive functioning of the spleen, resulting in excessive destruction of blood cells. "The expression of SCARB1, ALOX15, STAT6, and IL4 was up-regulated in hypersplenism, while the PPARγ expression was down-regulated." (PMID 39620221, 2024).
inverted papilloma (1 paper, 2025). An endophytic benign papillary epithelial neoplasm that results from the invagination and proliferation of epithelial cells in the underlying stroma.
iron deficiency (1 paper, 2014). "More specifically, Alox15 was identified as the most up-regulated mRNA in iron deficiency, and Reg family transcripts Reg1a, Reg 3a, and Reg 3b, were found to be markedly up-regulated in iron overload." (PMID 24465846, 2014). "The marked up-regulation of Alox15 mRNA expression in iron-deficient pancreas may be related to hypoxia due to iron-deficiency anemia in these animals." (PMID 24465846, 2014).
ischemic cardiomyopathy (1 paper, 2018). Ischemic cardiomyopathy is a cardiomyopathy in which a weakness in the muscle of the heart due to inadequate oxygen delivery to the myocardium with coronary artery disease being the most common cause. "Considering the well-described role of association of ischemic cardiomyopathy, fibrosis and arrhythmia, the increase in ALOX15/B under hypoxia suggested that fibroblasts might affect cardiomyocyte electrophysiology via ALOX15/B signaling." (PMID 30138423, 2018). "In summary, our results demonstrate that ALOX15/B signaling by hypoxic cardiac fibroblasts may play an important role in ischemic cardiomyopathy, by decreasing cardiomyocyte beating frequency." (PMID 30138423, 2018).
left ventricular hypertrophy (1 paper, 2010). Enlargement of the LEFT VENTRICLE of the heart. "Both ALOX15 and AGTR1 are likely to play important roles in inflammation, one of the primary putative mechanisms for the impact of air pollution on CVD and also an important mechanism involved in the development of left ventricular hypertrophy." (PMID 20308035, 2010).
lipid metabolic disorder (1 paper, 2017). "ALOX15 knockout prevented alcohol-induced liver damage via attenuation of oxidative stress, ER stress, lipid metabolic disorder, and cell death signaling." (PMID 28827690, 2017).
lung adenocarcinoma (1 paper, 2024). A carcinoma that arises from the lung and is characterized by the presence of malignant glandular epithelial cells. "We aimed to investigate the regulatory mechanism of the ferroptosis-related regulator ALOX15 by AQP4-AS1 and miR-4476 in lung adenocarcinoma (LUAD) and find new targets for clinical treatment." (PMID 39155888, 2024).
lung injury (1 paper, 2020). "The inhibition of ALOX-15 might inhibit inflammation and reduce vascular permeability by eliminating 12-HETE production in acute lung injury." (PMID 32256344, 2020).
macrosomia (1 paper, 2016). "The average methylation level of ALOX15 in Chr17: 4544507–4544627 was significantly up-regulated in the macrosomia group (P = 0.002)." (PMID 27888796, 2016).
male infertility (1 paper, 2020). The inability of the male to effect fertilization of an ovum after a specified period of unprotected intercourse. "These combined data confirm the link between ALOX15 activity and oxidative lipid damage in the male germline and provide support for ALOX15 as both a potential biomarker of male infertility risk and importantly, a powerful target for preventing oxidative stress-induced male infertility." (PMID 33396527, 2020). "Collectively, these data confirm the involvement of ALOX15 in the oxidative stress cascade of human spermatozoa and support the notion that increased ALOX15 abundance in sperm cells may accentuate membrane lipid peroxidation and cellular dysfunction, ultimately contributing to male infertility." (PMID 33396527, 2020). "Indeed, ALOX15 may be a useful marker for oxidative lipid damage and poor fertility, with the protective effects seen through pharmacological inhibition of ALOX15 highlighting the potential importance of targeting this enzyme for the prevention of oxidative stress-induced male infertility." (PMID 33396527, 2020).
metastatic tumor (1 paper, 2011). "ALOX15 converts arachidonic and linoleic acid to metabolites, a process that occurs during leukotriene biosynthesis, which was also indicated by biological processes identified in MDSCs from this 4T1 metastatic tumor group." (PMID 21853032, 2011).
myeloproliferative disease (1 paper, 2024). "The Alox15 gene, an ortholog of the human ALOX12 gene, develops the myeloproliferative disease characterized by pancytopenia attributed to hematopoietic stem cell dysfunction at the asymptomatic stage, followed by an abnormal expansion of myeloid cells in the spleen and bone marrow." (PMID 38731802, 2024).
osteosarcoma (1 paper, 2022). A usually aggressive malignant bone-forming mesenchymal neoplasm, predominantly affecting adolescents and young adults. "Finally, the survival curves of the three ferroptosis-related genes AKRIC2, AKRIC1 and ALOX15 in osteosarcoma patients were drawn." (PMID 36316355, 2022).
ovarian carcinoma (1 paper, 2022). A malignant neoplasm originating from the surface ovarian epithelium. "Although the mechanistic details for this expression regulation have not been explored, quantification of ALOX15 mRNA in the blood has been suggested as a marker for ovarian cancer." (PMID 35740398, 2022).
Parkinsonism (1 paper, 2023). Characteristic neurologic anomaly resulting from degeneration of dopamine-generating cells in the substantia nigra, a region of the midbrain, characterized clinically by shaking, rigidity, slowness of movement and difficulty with walking and gait. "ALOX15 was upregulated by α‐synuclein overexpression and acted as a fundamental risk factor in the development of chronic stress‐induced parkinsonism and neurodegeneration." (PMID 37622525, 2023). "Leonurine attenuates phospholipid peroxidation by preventing the assembly of the ALOX15/PEBP1 complex, thereby alleviating chronic stress‐induced Parkinson's disease susceptibility." (PMID 37622525, 2023).
polycystic ovary syndrome (1 paper, 2025). A disorder that manifests as multiple cysts on the ovaries. "A study suggested that PER1 promotes ferroptosis and dysfunctional lipid metabolism in granulosa cells in polycystic ovary syndrome (PCOS) by inhibiting sterol regulatory element-binding factor 2 (SREBF2)/arachidonate 15-lipoxygenase (ALOX15) signaling pathway." (PMID 41451215, 2025).
polyp (1 paper, 2020). A usually exophytic mass attached to the underlying tissue by a broad base or a thin stalk. "Moreover, patients with high combination levels showed significantly higher ALOX15 mRNA levels and higher eosinophil, but not neutrophil infiltration, in both polyp tissue and peripheral blood than patients with low combination levels (all P < 0.001)." (PMID 32973910, 2020).